ALB (albumin)
Diseases named in the same sentence as ALB in open-access papers (continued):
Sharing a sentence is not in itself a finding about the gene and the disease.
cardiovascular disease (continued). "The serum albumin level and number of patients with history of cardiovascular diseases (CVD) in the development data group were significantly higher than those of the validation data set (serum albumin: p = 0.001, history of CVD: p = 0.010)." (PMID 35041690, 2022). "Circulating fibrinogen-to-albumin ratio (FAR) has been proposed as a novel inflammatory biomarker and a cardiovascular disease risk predictor." (PMID 36371183, 2022). "Compared with those without myopenia, patients with myopenia in both early and established RA groups had higher levels of ESR and CRP, more active RA, a higher prevalence of cardiovascular diseases, and a lower level of serum albumin." (PMID 36505248, 2022). "The mechanism by which serum albumin potentially contributes to cardiovascular disease and mortality is likely multifactorial." (PMID 36013188, 2022). "A recent meta-analysis concluded that there is a robust and independent relationship with low plasma albumin and cardiovascular disease events." (PMID 34078390, 2021). "AGE levels are an independent predictor of overall and cardiovascular mortality as pre-existing cardiovascular disease, C-reactive protein, and serum albumin during a three-year follow-up in 109 HDF patients." (PMID 33921921, 2021). "Such signaling switching options are important for understanding the importance of albumin in both the prevention and development of cardiovascular diseases." (PMID 34638659, 2021). "Several studies have demonstrated that CAR, a new parameter of inflammation introduced in recent years, is superior to CRP and albumin levels alone in determining the inflammatory condition in cardiovascular diseases." (PMID 34406031, 2021). "This increased risk of mortality remained significant after adjustment for age, weight, creatinine, albumin concentration and cardiovascular diseases (HR = 1.83; 95% CI 1.08–3.1, p < 0.05)." (PMID 32393221, 2020). "Even after adjusting for age, cardiovascular disease and ARDS,plasma platelets and albumin levels were still associated with the risk ofnonsurvivors in the critical group (all p < 0.05)." (PMID 32490680, 2020). "The urine albumin-to-creatinine ratio (UACR) is a metric used to diagnose albuminuria and has also been shown to be associated with cardiovascular disease." (PMID 32100202, 2020). "Increase of albumin in blood can be observed after a chronic treatment with multiple drugs, in particular, statins have been reported to prevent cardiovascular disease through the increment of human serum albumin levels." (PMID 32445552, 2020). "This increased risk of mortality remained significant after controlling for age, weight, Norton score, creatinine, albumin concentration and cardiovascular diseases (HR = 1.83; 95% CI 1.08–3.1, p = 0.025)." (PMID 32393221, 2020). "Higher levels of the urinary albumin-to-creatinine ratio (UACR) are associated with adverse clinical outcomes, such as end-stage kidney disease, cardiovascular disease (CVD), and mortality." (PMID 31511532, 2019). "Several studies have shown that albumin was significantly correlated with adverse outcomes in cardiovascular diseases." (PMID 31827921, 2019). "Participants included versus excluded were less likely to be white or have cardiovascular disease, had slightly lower urea, hemoglobin and higher albumin." (PMID 25938230, 2015). "The HR for cardiovascular disease of albumin, CRP, and previous history of vascular disease was 2.040, 1.893, and 6.41 respectively." (PMID 26194096, 2015). "The model included age; body mass index; serum creatinine, albumin, total cholesterol and phosphorus levels; history of cardiovascular diseases; and arteriovenous fistula use." (PMID 26030526, 2015). "Higher urinary albumin excretion rates, even at levels well below the definition of moderately increased (previously ‘micro’) albuminuria (30 mg/24 h or a urine albumin:creatinine ratio of 30 mg/g), predict cardiovascular disease events and mortality." (PMID 24505486, 2014).
cardiovascular disease (continued). "Cardiovascular disease, prior catheter use, lowest tertile of albumin, highest tertile of hsCRP, and lowest tertile of fetuin-A were associated with primary patency loss in both patients with grafts and fistulas." (PMID 23557085, 2013). "An increased excretion of albumin in urine, often expressed as the albumin-creatinine ratio (ACR), is a risk factor for cardiovascular disease and an independent predictor of mortality in the general population." (PMID 22564356, 2012). "Patients who experienced a cardiovascular disease event during the observation period had significantly higher HbA1c and albumin values at the baseline investigation before dialysis treatment was started." (PMID 21625600, 2011). "The three different urine albumin methods studied provided similar information in relation to cardiovascular disease." (PMID 19609391, 2008). "The optimal cutoff value for MELD-Albumin in predicting the prognosis of HT patients identified in this study was 8.4, which slightly differs from previously reported optimal cutoff values in other cardiovascular diseases." (PMID 41602325, 2026). "C-reactive protein to serum albumin ratio (CRA) is used as a marker of cardiovascular disease." (PMID 40667402, 2025). "The role of albumin levels in cardiovascular disease has been frequently investigated." (PMID 40364067, 2025). "Previous studies have explored that various inflammatory indices, such as malondialdehyde (MDA), the systemic immune-inflammation index (SII, platelet × neutrophil/lymphocyte ratio), and the HALP (hemoglobin, albumin, lymphocyte, and platelet) score are predictive markers of cardiovascular disease." (PMID 40890594, 2025). "Relationship between erythrocyte distribution width and albumin ratio and cardiovascular disease." (PMID 41366972, 2025). "Inflammatory processes often reduce albumin (ALB) levels, a negative acute-phase protein, which is inversely associated with the occurrence of cardiovascular diseases." (PMID 40531765, 2025). "Previous history of cardiovascular disease (CVD) and low serum albumin were associated with MACE." (PMID 40824912, 2025). "The association between the neutrophil percentage-to-albumin ratio (NPAR) and all-cause and cardiovascular disease mortality in individuals with coronary heart disease (CHD) remains unclear." (PMID 41327740, 2025). "Patients with a history of cardiovascular disease have been reported to exhibit lower levels of total serum protein, albumin, total cholesterol, triglycerides, and high-density lipoprotein cholesterol, along with higher total white blood cell counts and serum BNP levels." (PMID 40218877, 2025). "Among 114 HD patients (57 cases, 57 controls), six independent risk factors were identified: afternoon HD session, presence of cardiovascular disease, and low levels of albumin (<37.35 g/L), creatinine (<828.65 μmol/L), urea (<28.05 mmol/L), and pre-dialysis blood glucose (<5.75 mmol/L)." (PMID 41293049, 2025). "The antioxidant properties of ALB in cardiovascular disease have been well‐established." (PMID 38269629, 2024). "Moreover, albumin (ALB) exhibits anti‐inflammatory, antioxidant, and antithrombotic effects, and low levels of ALB are associated with the development of various cardiovascular diseases." (PMID 38269629, 2024). "The 2 groups exhibited significant differences in terms of age, Cf-PWV, cardiovascular disease, peripheral arterial diastolic pressure, central arterial diastolic pressure, albumin, blood urea nitrogen, serum creatinine, LVEF, 25 hydroxyvitamin D3, C-reactive protein, and serum phosphorus." (PMID 39121296, 2024). "These analyses revealed that the prognostic value of the lactate/albumin ratio was consistent across these subgroups, after adjusting for all covariates, with notable interactions between the lactate/albumin ratio and sex, as well as history of cardiovascular disease." (PMID 39685564, 2024).
cardiovascular disease (continued). "Statistical analysis showed that significant differences were observed in terms of age, sex, marital status, BMI, disease duration, respiratory disease, cardiovascular disease, lesions, albumin, and hemoglobin among the groups of different grades (all P < 0.05)." (PMID 37076819, 2023). "It has been previously shown that low serum albumin is a risk factor for cardiovascular diseases, and this risk is independent of inflammation and body mass index." (PMID 37109621, 2023). "Studies have shown that low albumin levels increase cardiovascular disease and mortality rates." (PMID 37836479, 2023). "Also confirmatory evidence is that serum albumin exerts anti-inflammatory, antioxidant, anticoagulant and antiplatelet aggregation activity, which can join in several cardiovascular diseases." (PMID 37980510, 2023). "Taking into account the roles of inflammation and nutrition in a patient’s prognosis, the fibrinogen-to-albumin ratio (F/A ratio) was introduced as a prognostic factor for patients with cardiovascular diseases and cancers, with an increase indicating a microinflammatory condition." (PMID 35885582, 2022). "Serum albumin, as a negative acute-phase reactant, is a marker of systemic inflammation and has previously been shown to be associated with an increased risk of cardiovascular disease mortality in various patient subgroups." (PMID 35244369, 2022). "Plasma FFA could be bound to albumin, and the elevated serum FFA level can increase the risk of cardiovascular disease." (PMID 35479277, 2022). "Albumin is a simple and widely accepted marker of a person's nutritional status and contributes to excess morbidity and mortality across the entire spectrum of cardiovascular disease." (PMID 36462552, 2022). "The Framingham Heart Study, on the other hand, has evidenced that low-grade urinary albumin excretion was associated with an increased risk of cardiovascular disease and mortality in non-hypertensive, non-diabetic individuals." (PMID 35858835, 2022). "Furthermore, deposition of glycated/AGE-modified albumin has also been correlated with the hyperinflammatory process seen in cardiovascular disease." (PMID 35456942, 2022). "Basal hepatic oxygenation before HD might be affected by BMI, Hb levels, a history of cardiovascular disease, mean BP, serum albumin concentration, and the COP." (PMID 34673824, 2021). "The hepatic oxygenation before HD might be positively associated with the Hb level, mean BP, serum albumin concentration, and COP as well as BMI and a history of cardiovascular disease." (PMID 34673824, 2021). "Decreased levels of albumin, a negative acute-phase reactant, are associated with an increase in many cardiovascular diseases, including AF, independent of traditional risk factors." (PMID 34406031, 2021). "Furthermore, the most recent report in this area concluded that there is a relationship with low plasma albumin and cardiovascular disease." (PMID 34078390, 2021). "Participants with an elevated FLI were more likely to have higher age, T2D, a history of cardiovascular disease, a history of malignancy, higher blood pressure, lower NT‐ProBNP, lower alcohol intake, lower eGFR, higher urinary albumin excretion, higher glucose and higher insulin (all P < .05)." (PMID 34120339, 2021). "In summary, these findings suggest that a simple test of biomarkers (i.e., proBNP and ALB) may stratify the risk of prognosis in patients with CAD and provide treatment strategies aimed at reducing future cardiovascular disease morbidity and mortality." (PMID 34395522, 2021). "Plasma mannose levels have been tightly associated with atherogenesis, cardiovascular diseases, and mortality, and indirectly also with markers of inflammation (including CRP), creatinine, lower glomerular filtration rate, and with urine albumin excretion." (PMID 33187152, 2020).
cardiovascular disease (continued). "In addition, daily walnut consumption by CKD patients led to improvements of three factors associated with cardiovascular disease: systolic blood pressure, LDH cholesterol, and urinary albumin." (PMID 31881702, 2019). "In a 5-year study of long-term mortality after hospitalization for CAP, the authors found that age, cardiovascular disease, COPD, immunocompromised status, and low serum albumin level at admission were all independent risk factors for long-term mortality in CAP patients." (PMID 31291389, 2019). "Third, serum albumin levels in patients with cardiovascular diseases may have been affected by the body fluid volume because the blood samples were drawn during the acute phase." (PMID 30413062, 2018). "It is noteworthy, that lower ALB, aPOA1, TP and GGT levels, which may reflect increased proteinase activity, and higher AST/ALT ratios are always associated with both liver and cardiovascular disease." (PMID 28061459, 2017). "Under normal physiological conditions, on average 0.1–2 molecules of FA are bound to each albumin molecule; however, the molar ratio of FAs to albumin can reach up to 6-7 during fasting or extreme exercise or in patients with liver and cardiovascular diseases (e.g., acute myocardial ischemia)." (PMID 28356609, 2017). "For infectious mortality, only presence of cardiovascular disease [hazard ratio (HR) 2.367, 95% confidence interval (CI) 1.391–4.029, P = 0.001] and lower serum albumin level (HR 0.593, 95% CI 0.367–0.957, P = 0.032) showed statistical significance in multivariate Cox model." (PMID 27576771, 2016). "Minimal variation in laboratory data was observed in our study group, with the exception of albumin which is a recognized predictor of survival in elderly patients and CRP which is a risk factor for cardiovascular disease." (PMID 26289439, 2015). "The univariate model showed that the factors associated with 5-year survival were age, past history of cardiovascular disease, serum albumin level, and triglycerides level but not the modality of dialysis." (PMID 22701171, 2012). "However, recent studies on albumin's other functions revealed that albumin plays an important role in the pathogenesis of cardiovascular diseases." (PMID 19291315, 2009). "Indeed, albumin was shown to facilitate cellular efflux of unesterified cholesterol to extracellular acceptors such as HDL and LDL, and like serum HDL, to be inversely associated with cardiovascular disease." (PMID 40099968, 2025). "Furthermore, plasma albumin binds free fatty acids (each molecule capable of binding 2–6 moles of non-esterified fatty acids), participating in fatty acid and triglyceride regulation that subsequently influences cardiovascular disease progression." (PMID 41479660, 2025). "Low albumin levels may predict poorer health outcomes due to its role as a marker for systemic inflammation and nutritional status, which are crucial factors in managing OA and its comorbidities, such as cardiovascular diseases." (PMID 39639939, 2024). "Another factor, also of relevance to HDL, could be the serum albumin content, which was shown to facilitate cellular UC efflux to extracellular acceptors (e.g. HDL and LDL) and therefore to be inversely associated with cardiovascular disease." (PMID 38253888, 2024). "Since low serum albumin levels were shown to be associated with high mortality, including that due to cardiovascular diseases, they may also correlate with height loss, although no studies thus far have reported this connection." (PMID 37700384, 2023). "A previous meta-analysis demonstrated that low serum albumin levels are associated with an increased risk of death, not only in subjects free from cardiovascular diseases, but also in patients who already experienced cardiovascular diseases." (PMID 37316853, 2023).
cardiovascular disease (continued). "Thus, BUN and albumin have shown promising prognostic potential in cardiovascular disease and might be suitable biomarkers for predicting the outcomes of patients undergoing cardiac surgery." (PMID 35600476, 2022). "Even low levels of urinary albumin excretion can signify extensive vascular dysfunction and endothelial damage, which could be related to complications occurring in the context of metabolic abnormalities and cardiovascular diseases." (PMID 33686966, 2021). "Thus, oxidative stress in CKD patients increases serum ALB oxidation, which would elicit neutrophil respiratory burst, platelet aggregation, and endothelial inflammation, thereby worsening the pathological conditions and complicating cardiovascular diseases." (PMID 33804859, 2021). "In addition to baseline sCK levels, several covariates were independent risk factors for death: age (p<0.001), measured GFR (p<0.001), history of cardiovascular disease (p<0.001), serum albumin (p = 0.04) and prealbumin (p = 0.008), smoking status (p = 0.006) and proteinuria (p = 0.002)." (PMID 27248151, 2016). "The fibrinogen-to-albumin ratio (FAR), a novel marker reflecting inflammation and hemodynamics, has been proposed as a potential indicator for cardiovascular disease (CVD)." (PMID 41736825, 2026). "While BUN and albumin individually have established prognostic value, the utility of BAR in elderly patients with cerebrovascular and cardiovascular diseases remains underexplored." (PMID 41144534, 2025). "Previous studies have highlighted the importance of the CRP/albumin ratio (CAR) as a sensitive and accessible inflammatory index in cardiovascular disease." (PMID 40506944, 2025). "In comparison to BUN and albumin in isolation, the BAR is theoretically capable of providing a more accurate prediction of the ultimate prognosis of cardiovascular disease." (PMID 40290308, 2025). "The hemoglobin, albumin, lymphocyte, and platelet (HALP) score represents a meaningful predictor in many cardiovascular diseases." (PMID 40927085, 2025). "The fibrinogen-to-albumin ratio (FAR), a novel inflammatory marker, has demonstrated prognostic utility in cardiovascular diseases." (PMID 40604420, 2025). "Uric acid (UA), albumin (Alb), and C-reactive protein (CRP) have been studied for their pathophysiological relevance in cardiovascular disease." (PMID 41323647, 2025). "The C-reactive protein to albumin ratio (CAR) serves as a pivotal biomarker, demonstrating a strong correlation with adverse outcomes in cardiovascular disease (CVD)." (PMID 40128977, 2025). "Both low plasma albumin and increased CRP are strong indicators of cardiovascular disease and increased mortality in patients on dialysis." (PMID 39402451, 2024). "Lactate/albumin ratio, lactate, albumin, hs-cTnI, d-dimers, fibrinogen, age, APACHE II and SOFA scores, Charlson comorbidity index, as well as the presence of cardiovascular disease, were significantly higher in survivors as compared to non-survivors." (PMID 39685564, 2024). "The main risk factors included in previous PDAP clinical prediction models are age, UA, serum C-reactive protein (CRP)-to-Albumin ratio (CAR), NLR, RDW, DM, and cardiovascular disease." (PMID 37790129, 2023). "Sub-distribution hazard ratio (SHR) about hemoglobin, albumin, lymphocyte, and platelet (HALP) and cardiovascular disease (CVD) mortality." (PMID 37171338, 2023). "However, p-albumin is not an independent risk marker by itself but may reflect acute or chronic inflammation as found in a recent study of risk of cardiovascular disease." (PMID 33226880, 2020). "We analyzed the number and percentage of subjects who developed cardiovascular disease (CVD) events by stage and urine albumin level, which revealed that CVD events increased as the CKD stage and proteinuria increased." (PMID 30687877, 2019).